EFCAB12 (EF-hand calcium binding domain 12)
Synonyms: C3orf25
Tractability: PROTAC: ubiquitination databases record sites on it.
Gene: Protein-coding gene on chromosome 3 (129,401,321 to 129,428,636, reverse strand). Ensembl gene ENSG00000172771.
Subcellular location (Human Protein Atlas): Nucleoplasm; Midbody ring; Nuclear bodies
Gene Ontology:
Molecular function: protein binding; calcium ion binding
Genetic constraint (gnomAD): Loss-of-function variants: 44 observed, 53.3 expected, observed/expected ratio (o/e) 0.83, 90% interval 0.65 to 1.06. The upper end of that interval is the gene's LOEUF score, 1.06, which puts it in group 4 of 6, group 1 being the genes least tolerant of losing a copy. Missense variants: 646 observed, 728.02 expected, observed/expected ratio (o/e) 0.89, 90% interval 0.83 to 0.95. Synonymous variants: 269 observed, 283.55 expected, observed/expected ratio (o/e) 0.95, 90% interval 0.86 to 1.05.
Homologues: Orthologues: chimpanzee EFCAB12 (99% identical), macaque EFCAB12 (94% identical), pig EFCAB12 (68% identical), mouse Efcab12 (59% identical), rat Efcab12 (58% identical), tropical clawed frog efcab12 (24% identical), Caenorhabditis elegans B0563.7 (7% identical), Caenorhabditis elegans E02A10.3 (6% identical), Caenorhabditis elegans cal-3 (6% identical), Caenorhabditis elegans cal-1 (5% identical), Drosophila melanogaster TpnC4 (5% identical), Caenorhabditis elegans tnc-2 (5% identical), and 7 more. Paralogues in human: EFCAB7 (13% identical), CABP4 (8% identical), CALN1 (7% identical), EFCAB3 (7% identical), CABP1 (7% identical), CABP2 (7% identical), CETN3 (6% identical), CALM1 (6% identical), CALM2 (6% identical), CALM3 (6% identical), CETN1 (6% identical), CETN2 (6% identical), and 8 more.
Diseases named in the same sentence as EFCAB12 in open-access papers:
EFCAB12 is named in the same sentence as 2 diseases in open-access papers, as found by Europe PMC text mining. Sharing a sentence is not in itself a finding about the gene and the disease.
EFCAB12 shares sentences with these, for which no sentence is quoted: epilepsy (1 paper); Neurodevelopmental delay (1).